IL1B (interleukin 1 beta)
Diseases named in the same sentence as IL1B in open-access papers (continued):
Sharing a sentence is not in itself a finding about the gene and the disease.
tumor (continued). "These signaling molecules activate MMP-9, a matrix degrading enzyme involved in IL-1β-induced tumor invasion." (PMID 36430487, 2022). "Immunopreventive targeting of IL-1β decreases tumor burden, tumor cell proliferation, and tumor angiogenesis while increasing tumor cell apoptosis." (PMID 35471938, 2022). "Neutrophils, under these conditions, expressed cytokines such as TNF-α, Oncostatin M, IL-1β and IL-6, promoting tumour growth." (PMID 35406451, 2022). "Inflammasomes, potent inducers of IL-1β and IL-18 and pyroptosis, act as double-edged swords in cancers by producing tumor-promoting proinflammatory cytokines or facilitation of antitumor immune responses." (PMID 36386141, 2022). "Although NK cells are considered prototypical cytolytic anti-tumor effectors, when exposed to IL-1β, IL-23 and IL-2, ILC3s induced significantly higher cancer cell lysis compared to NK cells." (PMID 35300331, 2022). "IL1β enhances tumor invasion and dissemination directly, and also indirectly via inducing HIF1 expression followed by VEGF production." (PMID 36211375, 2022). "Findings have shown that IL-1β is secreted by immune cells, mainly myeloid cells, which represent an important component of the tumor microenvironment." (PMID 36531053, 2022). "IL-6 and IL-1β, two of the cardinal senescent cytokines, play central roles in tumor initiation and growth, partially explaining the aging-associated susceptibility to cancers." (PMID 35821823, 2022). "To further demonstrate that NLRP3/IL-1β signaling is a key mediator of tumor growth, we performed a rescue experiment in NLRP3 KO mice." (PMID 36439171, 2022). "IL-1α and IL-1β are cancer-promoting and drive angiogenesis, tumor progression, and tumor aggressiveness." (PMID 35565306, 2022). "The DAMPs, IL-1β and IL-18 released by pyroptosis of tumor cells can also effectively initiate CD8+ T cell expansion and promote NK cell recruitment, activate a tumor immune response, and improve the efficacy of immunotherapy." (PMID 36513682, 2022). "The proinflammatory cytokine interleukin-1β (IL-1β) is a potent driver of tumor progression by modulating tumor-promoting mechanisms such as angiogenesis, metastasis and immunosuppression." (PMID 35631400, 2022). "Overall, the future of HCC treatment modulating IL-1β and IL-18 should take into account the different backgrounds and a deep understanding of tumor biology and its interplay with the microenvironment integrated in a personalized medicine approach." (PMID 36289606, 2022). "While preclinical studies and clinical trials have almost only focused on the anti-tumor effects of anti-IL-1β, other research has examined improving the levels of IL-18 in the treatment of tumors." (PMID 35739593, 2022). "IL-1α and IL-1β can stimulate tumor growth and metastasis via upregulating the expression of angiogenic factors such as IL-8 and vascular endothelial growth factor (VEGF)." (PMID 35399416, 2022). "R848 delivered by complement C3-targeted liposomes triggered various signal cascades to increase the expression of cytokines and factors (such as TNF-α, IL-1β, IL-6 and IL-12), leading to the delay of tumor growth in 4T1 tumor-bearing mice." (PMID 35413927, 2022). "The presence of cytokines, especially factors such as IL-1β, near the probe implantation site have been shown to support immune reaction against the growth of tumor in other studies, suggesting a benefit of probe implantation in the vicinity of a tumor." (PMID 34852829, 2021). "When they combined anti-IL-1β treatment with anti-PD-1 checkpoint inhibitors, they observed abrogated tumor progression." (PMID 33806053, 2021). "In endometrial cells, these two bacteria can also induce the production of IL-1α, IL-1β, IL-17α, and TNFα, pro-inflammatory cytokines which are involved in the carcinogenesis of various tumours." (PMID 34357126, 2021).
tumor (continued). "The combination of vanadyl sulfate plus NDV also resulted in a significant decrease in IL-1β, a cytokine that has been shown to play a key role in carcinogenesis and tumor progression in the B16-F10 hepatic metastasis model." (PMID 33614913, 2021). "At the endpoint of the experiment, the expression levels of tumor proliferation, migration, and invasion-related proteins in the IL-1β/NF-κB pathway were detected by Western blot assay." (PMID 34055197, 2021). "Additional groups utilizing syngeneic murine tumor model systems have reported on the anti-tumor properties of IL-1β." (PMID 34638239, 2021). "Taken together, pro-inflammatory cytokine IL1B in the tumor microenvironment can upregulate ELF3 in LUAD tumor cells, which augments the activation of NF-κB pathway to favor tumor cell survival and growth." (PMID 33144684, 2021). "The nano-drug can also inhibit the expression of TNF-α/IL-1β and reshape the tumor cell TME to enhance the anti-tumor effect and reduce the toxic and side effects caused by drug alone." (PMID 34120620, 2021). "Although HIFU does not appreciably activate an adaptive immune response, it induced inflammation via upregulation of Il1β and Il6, which leads to recruitment of MDSCs and subsequent tumor regrowth." (PMID 33441763, 2021). "It was also observed that tumor-associated neutrophils are involved in regulating tumor development, while IL-1β and IL-18 route neutrophils to tumor sites." (PMID 34837692, 2021). "For instance, IL-1β/IRAK4 is the feedforward signal of the tumor matrix with a very high expression level in cancer development, and disrupting the tumor-stroma IL-1β/IRAK4 feedforward circuitry improves the chemotherapy in PDAC." (PMID 34067040, 2021). "Amongst some of the well-studied growth factors, chemokines, and cytokines, TNF-α and IL-1β play a central role in inflammation that has been recognized as a key step in angiogenesis, tumor survival, and local invasiveness." (PMID 34571989, 2021). "Upon arrival in the bone environment, contact between tumor cells and osteoblasts or myeloid cells increases the secretion of IL-1β by all three of these cell types." (PMID 34602858, 2021). "Another study also showed that the expression of IL-1β by MICs in BC was significantly associated with longer relapse-free survival and overall survival, while the lack expression of IL-1β by MICs are associated with the worst prognosis, and may contribute to tumor immune escape." (PMID 34602858, 2021). "In pancreatic ductal adenocarcinoma as well, the recruitment of neutrophils by CAA-secreted IL-1β is relevant in tumor progression." (PMID 33917351, 2021). "In vitro invasion assay confirmed that irradiation targeting D2A1 tumor and its microenvironment increased the levels of plasma IL-1β, promoted the infiltration of tumor cells and the development of lung metastasis and increased the activity of MMP-2 and MMP9." (PMID 34602858, 2021). "Blocking IL-1β reversed the immunosuppressive tumor microenvironment of breast cancer mouse models and showed synergistic antitumor activity with anti-PD1." (PMID 33801846, 2021). "This transcription is responsible for the secretion of interleukins including: IL-1b, IL-6, and IL-8; Tumor Necrosis Factors: TNF-a, TNF-b; inducible cyclooxygenase (COX-2 favor prostaglandin synthesis); and inducible nitric oxide synthase (iNOS)." (PMID 34682182, 2021). "IL-1β and iNOS levels significantly reduced in co-cultures with tumor cells along with a decrease in phagocytosis." (PMID 33937269, 2021). "In samples taken from the tumour tissue, the RQ values of IL-1β and IL-6 were higher in patients with pT1 stage vs. pT3 stage, while those of IL-17 were higher in pT3 vs. pT2 patients." (PMID 33658555, 2021). "In contrast, myeloid-derived suppressive cells (MDSC), pro-angiogenic Type-2 tumor associated macrophages (TAM) and/or their derivative cytokines IL-6, TNF, IL-1β and IL-23 are generally recognized as dominant tumor-promoters." (PMID 34930302, 2021).
tumor (continued). "We have demonstrated that EVs released from advanced-stage of PCa cells, by activating the inflammasome cascade and interleukin-1β (IL-1β) production, alter the immune/inflammatory response of microenvironment-residing cells in a tumor promoting fashion." (PMID 34070682, 2021). "As the first-line sentinel of host defense for tissue homeostasis, neutrophils rapidly migrate to the tumor site in response to many signals like IL-8 and IL-1β." (PMID 34671362, 2021). "For example, overexpression of IL-1β in tumor cells has been shown to increase their migration as well as their invasion through Matrigel towards osteoblasts." (PMID 33809315, 2021). "IL-1β inhibits tumor growth by promoting tumor cell death; this is accomplished by priming CD8+ T cells or stimulating CD4+ T cells toward Th1 response." (PMID 34829795, 2021). "Observed reduction of IL-1β and IL-6 expression at the genetic level in tumour lesion are consistent with those of previous studies." (PMID 33658555, 2021). "Recent evidence suggests that IL-1β has a dual role in cancer development: On the one hand, it initiated pro-inflammatory anti-tumor immune responses by activating tumor antigen-specific TH1 and TH17 cells and facilitated tumor regression." (PMID 35097027, 2021). "Both, IL1β and TGFβ1, along with some more soluble factors, have been described to be molecules that mediate the crosstalk between tumor cells and fibroblasts and are responsible for the activation state of the latter." (PMID 34066976, 2021). "Increased expression of IL-1β allows for the recruitment of lymphocytes to prevent direct contact between EBV-associated cytotoxic T cells and the tumour cells, thereby inhibiting apoptosis." (PMID 34956172, 2021). "Upregulation of the NLRP3 inflammasome in OSCC cells was reported to correlate positively with IL-1β expression level, tumour growth, and lymph node metastatic status." (PMID 33918087, 2021). "It has been proposed that IL-1B promotes the recruitment of anti-tumour neutrophils to the lung metastatic niche, consequently reducing metastasis." (PMID 34290237, 2021). "DOX administration in tumor-bearing mice significantly ameliorated the tumor-induced upregulation of IL-1β, IL-6, TNF-α, and Mcp-1." (PMID 34445729, 2021). "IL-1β is regulated by the IL-1RI/NF-κB pathway and is a tumor-related factor leading to MDSC amplification and migration." (PMID 34975496, 2021). "Chronic exposure to TNF-α and IL-1β leads to tumor progression as these cytokines are pro-angiogenic and promote epithelial-mesenchymal transition (EMT) and cell migration." (PMID 34571989, 2021). "The GSDME -induced pyroptosis can release many IL-1β and other inflammatory factors into the surrounding normal liver cells, inducing the normal cells into the tumor cells in inflammatory conditions." (PMID 34820376, 2021). "The mRNA expression of IL-1β in tumor and normal tissues from the cancer genome atlas (TCGA) dataset and 83 CRCs with matched normal samples in our laboratory were analyzed." (PMID 33980323, 2021). "In conclusion, tumor colonization is counteracted by ROS-activated and IL-1β-secreting tissue neutrophils." (PMID 34257370, 2021). "IL-1β is associated with the development of OSCC, and its elevated levels have also been detected in samples of this tumor." (PMID 34442627, 2021). "Interleukin-1β (IL-1β)–mediated inflammation suppresses antitumor immunity, leading to the generation of a tumor-permissive environment, tumor growth, and progression." (PMID 33649199, 2021). "It is worth mentioning that the peptide LyeTx I-b significantly decreased the expression of IL-1β in tumor and lung tissues, with an increase in the levels ofIL-10 anti-inflammatory cytokines in primary tumor, as observed with other AMPs." (PMID 34572719, 2021).
tumor (continued). "Here we describe the IL1β-mediated interplay between cancer cells and normal colonic myofibroblasts (NCFs), which bestows differential sensitivity to cytotoxic drugs on tumor cells." (PMID 34066976, 2021). "For example, IL‐1β is induced by the NF‐κB signaling pathway to promote inflammation, cancer cell proliferation, angiogenesis, and tumor metastasis." (PMID 34977871, 2021). "The accumulation of MDSC in tumor-bearing individuals has been shown to depend on the inflammatory mediators IL-1β, IL-6, and Prostaglandin-E2 (PGE2)." (PMID 33917501, 2021). "Based on previous studies and cytokine levels quantified by ELISA, we focused on the inflammatory cytokine IL-1β in the tumor microenvironment to explore in-depth mechanisms." (PMID 34055197, 2021). "Together, the different observations propose that the persistent presence of TNFα and IL-1β at the tumor site contributes to chronic inflammation in BC and that the two cytokines play key roles in advancing disease course." (PMID 33806906, 2021). "ICAFs are driven by tumor secretory factors, such as Interleukin-1 alpha (IL-1α) and Interleukin 1 beta (IL-1β), and gather at the edge of the tumor." (PMID 34067040, 2021). "Although IL-1β appears to be involved in tumor invasion and angiogenesis, its role in the context of cancer treatment has also been reported." (PMID 34829795, 2021). "IL1β-mRNA-primed wild-type B220+CD11c+NK1.1+ cells reduced the number of metastatic tumor cells homing into the lungs." (PMID 34135341, 2021). "The role of IL1B in tumor progression has been well established and it is necessary for cellular homeostasis." (PMID 34083590, 2021). "TAMs control tumor angiogenesis by sensing hypoxia conditions, producing IL-1β and increasing VEGFA expression, which are regulators of vascular permeability and tumor angiogenesis." (PMID 33766119, 2021). "NF‐κB is mainly activated in these cells to induce the expression of cytokines (TNFα, IL‐1β, IL‐6, etc.), thereby promoting tumor survival and proliferation." (PMID 34977871, 2021). "Dectin-1 derived from particulate β-glucan converted M2 bone marrow-derived macrophages into M1-like phenotype, which expresses proinflammatory cytokines such as TNF-α, iNOS, IL-1β, and IL-6 to inhibit the development of the tumor." (PMID 34094602, 2021). "To understand the properties of the microbiota found in this study, we analyzed the correlation by taking previously reported results (DAI score, ELISA levels of MPO and IL-1β, and tumor number) from the same set of experiments." (PMID 34249773, 2021). "This review focuses on fate-determining roles of the inflammasomes and the principal downstream effector cytokine, IL-1β, in the tumor microenvironment." (PMID 33686176, 2021). "It should be pointed that regulation of IL-1β expression is depending on complex interactions between tumor cells and infiltrating host inflammatory cells like lymphocytes and macrophages." (PMID 33658555, 2021). "As a result of the pleiotropic effect of IL-1β, molecules able to modulate its activities have been proposed as candidates for anti-tumor therapy approaches." (PMID 34070682, 2021). "Secretion of IL-1β by CAFs activates NF-κB signaling in the tumor cells, thereby increasing CCL22 expression." (PMID 33925575, 2021). "Appropriately, colon biopsies from TAK-242 and Abx treated mice secreted considerably lower amounts of tumor-promoting cytokines, such as IL-1β and TNF-α." (PMID 34025672, 2021). "NOD-like receptor protein 3 (NLRP3)-inflammasome activation, interleukin-1β (IL-1β) secretion, and cancer cell-released extracellular vesicles (EVs) contribute to the establishment of tumor microenvironment." (PMID 34070682, 2021). "The NLRP3 inflammasome is an innate immune mediator responsible for active interleukin (IL)-1β biosynthesis and secretion, which is critical for tumor development and immunity." (PMID 34357109, 2021).
tumor (continued). "It has been shown that IL-1β secreted by macrophages increases NK cytotoxicity, while IL-1β produced by tumor cells impairs NK cell development and functions, recruiting MDSCs." (PMID 35008679, 2021). "Succinate is also an inflammatory signal and induces IL-1β expression in the tumor microenvironment, which can lead to a switch of M1 type macrophages, participating actively in anti-tumor immunity." (PMID 34957538, 2021). "To address these concerns, we measured the cytokines (such as TNF-α, IL-1β and IL-6) after we intravenously administered DMVs at 0.6 mg of DMVs which was the same dose used in the tumor therapy." (PMID 33537088, 2021). "Increased IL-1β levels in primary tissues and metastatic sites have been detected in a spontaneous murine mammary gland tumor model, suggesting that the IL-1β pathway promotes tumor growth and metastasis." (PMID 34064909, 2021). "In lung cancer, caspase-1 inhibition results in the reduction of IL-1β and IL-18, leading to tumour-induced immunosuppression in the lung microenvironment." (PMID 33918087, 2021). "By activating the ERK signaling pathway and phosphorylation of c-Jun/Fos, c-Myc, and E-26-like protein 1, IL-1β also promotes cell survival and tumor progression." (PMID 33925575, 2021). "Activated astrocytes, in turn, produce IL-6, TNF-α, and IL-1β, which promote tumor cell proliferation." (PMID 33466236, 2021). "While nigericin induced cell death in tumor cells producing low levels of IL-1β and IL-18, increased proliferation was found in cancer cells producing, high levels of IL-1β and IL-18." (PMID 34577552, 2021). "The effect of samples to reduce the levels of IL-1β, which is a marker molecule favoring tumor cells, would be beneficial in the screening of cytotoxic activity." (PMID 34883728, 2021). "Inflammation induced by microbial or danger signals affects all stages of tumor development, and proinflammatory cytokines, including IL-1β and IL-6, are important mediators of inflammation-induced tumorigenesis." (PMID 33534121, 2021). "Previously, we demonstrated that tumor cells release various amounts of IL-1β based on their ability to activate NLRP3." (PMID 34577552, 2021). "In our study, we found that IL-1β plays an important role in regulating the tumor microenvironment of PAAD." (PMID 34150748, 2021). "MDSCs are actively drawn and activated in the tumors by various secretory products like PGE2, VEGF, GM-CSF, IL-6, TNF-α, IL-10, and IL-1β elaborated by TIICs, CAFs, and the tumor cells themselves." (PMID 33996630, 2021). "IL1B not only activates antigen-presenting cells, thereby initiating an adaptive anti-tumor response, but also promotes tumor growth, metastasis as well as angiogenesis upon activation by tumor-infiltrating macrophages." (PMID 33690729, 2021). "In line with impaired M2-like macrophage infiltration, we observed a decrease in CD34+ blood vessels in tumours growing in an IL-1B ablated microenvironment." (PMID 34290237, 2021). "IL1β and other pro-inflammatory cytokines, such as IL-6 and IL-8, which are known to promote inflammatory signaling, tumor growth, and metastasis, are also produced by cancer-associated fibroblasts (CAFs)." (PMID 34901003, 2021). "The tumor-infiltrating immune cells, such as neutrophils, dendritic cells, and TAMs, further promote the secretion of IL-1β in the tumor microenvironment." (PMID 34684819, 2021). "Studies have shown this process to support the recruitment of other myeloid cells to the tumor bed and promote tumor invasiveness and metastasis in an IL-1β-dependent manner." (PMID 34638239, 2021). "IL-1α’s action is mainly immunostimulatory, while IL-1β exhibits a pro-inflammatory role, especially in the early phases of tumor development." (PMID 33557173, 2021). "High levels of plasma IL-1β and tumor-derived IL-1β significantly correlate with tumor invasiveness and bone metastasis in BrCa and PrCa, which translates into a poor prognosis." (PMID 34064859, 2021).